CTLA4 (cytotoxic T-lymphocyte associated protein 4)
Diseases named in the same sentence as CTLA4 in open-access papers (continued):
Sharing a sentence is not in itself a finding about the gene and the disease.
tumor (continued). "Our results showed that combining α-PD-1 with α-CTLA-4 antibody, but not α-Lag3, resulted in significantly enhanced tumor-free survival relative to that of mice treated with either antibody alone." (PMID 31533840, 2019). "Unlike CTLA-4, the PD-1 expression is on tumor cells and other healthy cells throughout the body, a large portion of which are myeloid cells in the TME." (PMID 30941175, 2019). "The combination of anti-OX40 and anti-CTLA-4 antibodies has been tested in some tumor models, and the resulting anti-tumor effect was found to be on par with ATOR-1015 (data not shown)." (PMID 30975201, 2019). "MHC-IIhi DCs was discovered in the tumors of Bifidobacterium-treated mice; orally feeding B. fragilis induced Th1 immune response in the tumor-draining lymph nodes and catalyzed the maturation of DCs in the TME, facilitating the restoration of the clinical response to CTLA-4 blockade." (PMID 32010123, 2019). "ATOR-1015 and the anti-OX40 antibody were found to selectively bind to the tumor-infiltrating cells, whereas this was not seen with the anti-CTLA-4 antibody." (PMID 30975201, 2019). "Nude mice do not have T cells, allowing for evaluating the function of tumour cell‐intrinsic CTLA4 in the absence of adaptive immunity." (PMID 30378264, 2019). "Recently, it has been shown that using conditional knockout mice has demonstrated that lack of CTLA-4 in Treg cells prevents immune system self-tolerance and impairs the inhibitory role of Treg cells in tumor immunity." (PMID 30693029, 2019). "As tumor numbers increased, immune checkpoints including PD-1, TIM-3, TIGIT, and CTLA-4 increased." (PMID 31801611, 2019). "By targeting both OX40 and CTLA-4, ATOR-1015 induces an enhanced and tumor-directed Treg depletion, which may translate into a better clinical response both in terms of efficacy and safety." (PMID 30975201, 2019). "By contrast, systemic treatment with anti-PD-1 and anti-CTLA-4 mAbs failed to control BP tumor progression." (PMID 31799501, 2019). "Interestingly, albeit used initially as a control, this analysis revealed that IT treatment with anti-CTLA-4 led to even more robust T cell, cytotoxic cell, and macrophage responses, and an increased CD8 T-cell tumor infiltration." (PMID 31804466, 2019). "Accordingly, pharmacological blockade of C5aR1 in a syngeneic model of lung cancer impaired tumor growth, decreased the percentage of splenic MDSCs, and downregulated immunosuppression-related genes including ARG1, IL6, IL10, CTLA4, LAG3, and PDL1 within the tumor milieu." (PMID 31001273, 2019). "We provide evidence that anti-CTLA-4, with or without radiation therapy, can activate synergistic anti-tumor immunity in this patient population." (PMID 31287031, 2019). "Clinical studies such as the combination of DC pulsed with the tumor antigen NY-ESO with or without CTLA-4 blockade (NCT02070406) will answer the question on the relevance of this mechanism in vivo." (PMID 30788290, 2019). "Successful activation of anti-tumor immunity in our patient cohort by adding anti-CTLA-4 is, perhaps, not surprising, but remarkable nevertheless for this population with few effective immunotherapy options." (PMID 31287031, 2019). "Anti-CTLA4 therapy alone did not delay tumor growth or improve survival whereas RT alone delayed growth of the primary lesion." (PMID 30895168, 2019). "Unlike Tregs, surface expression of CTLA-4 by both naïve and anti-tumor CD4+ and CD8+ effector memory T cells only occurs following major histocompatibility complex (MHC)-dependent activation of these cells by APCs." (PMID 31616428, 2019). "Notably, we found that cells expressing CTLA-4, the first approved checkpoint blockade target, displayed a generally low frequency (<20%) in both CD4 and CD8 T cell populations in the tumor and peripheral blood across eight cancer types." (PMID 31709176, 2019). "Furthermore, in a regimen combining either the virus or LTX-315 with anti-CTLA4, the LTX-315 was superior in controlling tumor growth." (PMID 31799501, 2019).
tumor (continued). "Moreover, in a tumor progression situation the miR-424 can directly block the binding of PD1/PDL1 and CD80/CTLA-4 action and thereby induce tumor suppression." (PMID 31337863, 2019). "The targeted release of anti-CTLA-4 within tumors was found to deplete tumor Tregs, without affecting tissue-resident Tregs, thus not inhibiting their antitumor activities." (PMID 31717326, 2019). "The expression of genes encoding immune checkpoint molecules, such as programmed cell death ligand 1 (PD‐L1), programmed cell death 1 (PD‐1), cytotoxic T‐lymphocyte antigen (CTLA)‐4, and CD8A, which is a marker of tumor‐infiltrating lymphocytes, was investigated." (PMID 31240875, 2019). "It is not fully understood why T cells fail to inhibit tumor growth without immunotherapies and why a significant subgroup of patients does not respond to CTLA4 or PD-1 blockade." (PMID 31275310, 2019). "CTLA-4 and TIGIT act as tumor suppressors and thus, modulate the immune response in the TME." (PMID 31801611, 2019). "CTLA-4 is constitutively expressed by Tregs, but it can also be upregulated by other T-cell subsets, especially CD4-positive T-cells upon activation, as well as tumor cells." (PMID 31581738, 2019). "It is believed that CTLA-4 impacts on the stage of T-cell activation mainly in the draining lymph nodes by removing CD80/CD86 from the surface of antigen-presenting cells, thus decreasing the ability to effectively stimulate tumor-specific T cells." (PMID 31581738, 2019). "Surprisingly, we saw enhanced antitumor responses with anti-CTLA-4 treatment, where most 4MOSC1 tumor-bearing mice showed complete responses and no tumor reoccurrence." (PMID 31804466, 2019). "Allison and Honjo, winners of the Nobel Prize in physiology and medicine in 2018, showed that cytotoxic T lymphocyte antigen 4 (CTLA-4) and programmed cell death protein 1 (PD-1) act as negative immune regulatory factors and inhibit anti-tumor immune response." (PMID 31443694, 2019). "In some tumor models, anti-TIM3 has almost the same effect as anti-PD-1 and anti-CTLA-4." (PMID 31708918, 2019). "In a B16-OVA melanoma tumor model, CTLA-4 combined with cryoablation rescued 80% of the mice post tumor re-challenge as opposed to 40% only post cryoablation." (PMID 31608067, 2019). "Intratumoral LTX-315 treatment significantly delayed KP tumor progression, which systemic treatment with anti-PD-1 and anti-CTLA-4 mAbs failed to do." (PMID 31799501, 2019). "Of note, the IL2 cytokine and the IL2-modified version have been described as being able to synergize with anti-CTLA4 and anti-PD1/PDL-1 antibodies in terms of tumor control, but only a combination of the IL2-based cytokine with CTLA4 is able to re-activate NK cells in vivo." (PMID 31614774, 2019). "Tumor uptake was significantly higher in mice that received radiolabeled anti-CTLA-4 compared to mice that received radiolabeled non-specific IgG." (PMID 31696402, 2019). "CTLA-4 and PD-1 contribute to related but non-overlapping immunoregulatory pathways, and in patients with other tumor types, combinatorial therapy has triggered cancer regressions after progression on anti-PD-1 therapy." (PMID 31287031, 2019). "Since immunotherapy regimens most commonly employ monoclonal antibodies targeting regulatory checkpoints, we determined the expression levels of four immune checkpoints (CTLA4, LAG3, PD1, and TIM3) on tumor infiltrating T cells, and PD-L1 expression on B6CaP tumor cells." (PMID 31839878, 2019). "Furthermore, combined treatment with anti-PD-1 and anti-CTLA-4 antibodies produced higher CD4+ T cell, CD8+ T cell and DC infiltration into the tumor." (PMID 31291357, 2019). "In view of its deregulated expression in tumor-infiltrating lymphocytes, LAG3, together with the additional immune checkpoint inhibitors CTLA4 and PD1, is considered a major target in order to reverse the immunosuppression typically mounting in oncologic diseases." (PMID 31623599, 2019).
tumor (continued). "Given that increased antigen presentation and interferon signaling, which suggested an elevated tumor immunogenicity in APR tumors, we next sought to combine immune checkpoint blockades (ICB, anti-CTLA4, and anti-PD-1 antibodies) to overcome or prevent the resistance to Ab + Pal treatment." (PMID 31444334, 2019). "With a glimpse at the recent advances of tumour immunotherapy, the combination paradigms between conventional cancer-treatment modalities (e.g., RFA14, PDT49 and PTT50) with CTLA-4 or PD-1/PDL-1 could maximise benefits of cancer immunotherapies." (PMID 31048681, 2019). "We showed that the suppressive function of tumor-infiltrating Treg cells was enhanced by the increase in their relative proportion and by the upregulation of the expression of inhibitory receptors, such as PD-1, TIM-3, and CTLA-4." (PMID 31801611, 2019). "However, for targets such as CTLA-4, TIGIT, and VISTA, competent Fc is required for optimal anti-tumor immune responses in various mouse models." (PMID 30863404, 2019). "For example, in NSCLC patients undergoing PD-1 or PD-1/CTLA-4 inhibitor treatment, it was detected that both TMB and candidate neoantigen level of post-progression tumor tissue were higher compared to pre-immunotherapy tumor tissue." (PMID 30473928, 2018). "Importantly, in mouse syngeneic models that respond poorly to mAbs targeting either PD-L1 or CTLA-4, combination with MEDI9197 significantly improved anti-tumor activity when compared to either monotherapy alone." (PMID 29910800, 2018). "In Ctla4h/m mice expressing both human and mouse CTLA4 genes, anti-CTLA-4 antibodies that bind to human but not mouse CTLA-4 efficiently induce Treg depletion and Fc receptor-dependent tumor rejection." (PMID 29472691, 2018). "Tumor-intrinsic activation of WNT/β-catenin signaling pathway results in subdued CCL4 expression and subsequent precluded dendritic cell (DC) recruitment and DC-mediated T-cell activities, thus leading to resistance to anti-PD-L1 and anti-CTLA-4 therapies." (PMID 30294272, 2018). "As CTLA-4 has a much higher affinity to CD80 and CD86 than CD28, the outcome will also be influenced by CD80/86 expression and subsequent ligation in the TDLN and tumor sites." (PMID 30542345, 2018). "As a result, CTLA-4-blocking antibodies augment the binding of CD80/86 to CD28 rather than to CTLA-4 and also deplete Tregs in the tumor environment that consistently express CTLA-4 13,14." (PMID 30135516, 2018). "No local tumor recurrence was observed, but mice succumbed of lung metastasis with the largest increase in survival (vs. untreated) in mice given RT+anti-CTLA-4 (p=0.0041)." (PMID 30400822, 2018). "siRNAs blocking the PD-1/PD-L1 or CTLA-4/CD80, /CD86 pathways could reduce the metastasis of tumor cells." (PMID 30564277, 2018). "Activation of effector T-cells by CTLA4 is not antigen-specific, and the details of the process of tumour clearance and aggression of bystander cells are not completely understood." (PMID 29642948, 2018). "It's worth noting that the best efficacy for anti-CTLA-4 blockade was achieved in combination with GM-CSF+ tumor cell vaccination two decades ago by the lab of the newly Nobel laureate Dr. James Allison." (PMID 30619378, 2018). "Since CTLA-4 ligands (CD80 and CD86) are only expressed on APCs, but not on the tumor cell surface, the CTLA-4-mediated inhibition of T cell activation occurs in secondary immune organs (lymph nodes)." (PMID 30519541, 2018). "Taken together, we suspect that such a highly immune-mediated tumor environment, especially as related to HPV infection, may have provided the context in which inhibition of both CTLA-4 and PD-1/PD-L1 pathways led to significant antitumor effects." (PMID 29743117, 2018).
tumor (continued). "The results also showed that the percentage of total CD8+ cells increased and the more severely exhausted PD1+CTLA-4+CD8+, PD1+Tim-3+CD8+, PD1+TIGIT+CD8+, and PD1+LAG-3+CD8+ T cells in the tumour infiltrating CD8+ T-cell population decreased after vvDD-IL-2-RG treatment." (PMID 30410056, 2018). "Both anti-PD-1 and anti-CTLA-4 therapies appear to be more effective in patients with pre-existing anti-tumor immunity, suggesting that, in patients without such immunity, these drugs are unable to mediate anti-tumor immune responses de novo." (PMID 29644214, 2018). "By secreting cytokines, chemokines or growth factors, as well as up-regulating specific surface receptors, e.g., PD-L1, CTLA-4, carcinoembryonic antigen-related cell adhesion molecule 1 (CEACAM1), and others, tumor cells become competent in dampening and finally escaping the immune system." (PMID 30577587, 2018). "In certain cases, however, radiotherapy + anti-CTLA-4 of patients with high tumor PD-L1 levels (type I TME) did not respond, contrary to anti-PD-1 treatment alone." (PMID 30191140, 2018). "Tumors grew progressively in untreated mice, but anti-PD-1 mAb treatment inhibited tumor growth, while anti-CTLA-4 had no apparent effect in this model." (PMID 29348598, 2018). "HCC-derived Tregs down-regulated CD80/86 expression on splenic DCs in a CTLA-4 dependent manner, and inhibition of CTLA-4 could prevent the Treg-mediated suppression in anti-tumor immune responses." (PMID 29843754, 2018). "Cytotoxic T lymphocyte protein 4 (CTLA-4) and programmed cell death protein-1 (PD-1) are immune checkpoints that inhibit the T-cell response, which provide the escape mechanism of the tumour cells to T-cell antitumour activity." (PMID 30027089, 2018). "CTLA-4 is another immunoinhibitory receptor expressed on activated T cells; when it combines with its ligand B7 on dendritic cells, the complex CTLA-4-B7 acts as a checkpoint inhibitor for anti-tumor T cells." (PMID 29420595, 2018). "Since there was a low number of cases in Group III, ILCs’ expression of CTLA-4 was not discussed based on the tumor grades in detail as in Group II." (PMID 29672601, 2018). "Limited preclinical data showed that anti-CTLA-4 did not significantly alter tumour growth except when Tregs were depleted." (PMID 29848327, 2018). "Tumors on mice treated with anti-CTLA-4 antibody alone showed good responses by suppression of tumor growth, which was not impaired by the combination treatment with karonudib." (PMID 30042422, 2018). "The combination of anti-CTLA4 antibodies with fractionated irradiation (3 × 8 Gy or 5 × 6 Gy), but not single-dose irradiation (20 Gy), showed tumor growth delay outside the field of irradiation in preclinical models." (PMID 29350049, 2018). "In preclinical models of PDAC, anti-PD1 and anti-CTLA4 antagonists showed limited efficacy as monotherapies to restrain tumor growth, but the use of these agents in combination with CSF1R blockade resulted in tumor regression." (PMID 29594035, 2018). "In a study of radiation therapy combined with checkpoint blockades, anti-CTLA4 functions most effectively when administrated ahead of radiation, but anti-OX40 must be given after radiation to improve treatment efficacy in a mouse tumor model." (PMID 30533489, 2018). "Recent studies suggested that in vivo CTLA-4 antibodies do not function by blocking CTLA-4 inhibition but by depleting Treg cells in the tumor microenvironment via Fc-receptor mediated mechanisms." (PMID 30201974, 2018). "Following culture of these cells for 3 days with or without either a-CTLA4-TGFβRII or a-CTLA-4, tumor antigen-reactive T cells (CD3+/CFSElow/IFNγ+) were quantified by immunophenotype analyses." (PMID 29467463, 2018). "As summarized in a recent review addressing the immune checkpoint inhibitors in Tregs, these cells constitutively express immune checkpoints like CTLA-4 but also PD-1, BTLA, LAG-3, and TIM-3, and upregulate inhibitory receptors during activation and at tumor sites." (PMID 30233564, 2018).
tumor (continued). "Similar observations were reported for anti-CTLA-4, anti-GITR, and anti-OX40 antibodies in murine systems demonstrating that binding to activating FcγR results in depletion of intra-tumoral Tregs and contributes to anti-tumor activity." (PMID 30061887, 2018). "Nonetheless, although venushigh CD8+ T-cells were detected in mice receiving anti-PD-1, anti-CTLA-4, the anti-PD-1/4-1BB combination or anti-CD4 mAbs, tumor growth was still not controlled in the anti-CTLA-4 group." (PMID 29348598, 2018). "Because anti-PD-1 mAb and anti-CTLA-4 mAb could promote intratumoral TILs, ICB treatment prior to ACT may increase the number of TILs that can be derived from a tumor biopsy." (PMID 29482595, 2018). "We identity CD94, CD137(4-1BB), CD355 (CRTAM) as specific markers for antigen-specific activation of T-cells by autologous tumor cells, whereas other “check point” markers such as CTLA-4, PD-1, Tim3, CD39, CD103 were up-regulated by stimulation with unrelated tumor cells." (PMID 30400835, 2018). "We hypothesize that the addition of IL-2, anti-CTLA-4, or anti-PD-1/PD-L1 may reinforce CD8+ T cell function in the tumor microenvironment to further ameliorate antitumor efficacy of M-ILP." (PMID 30560089, 2018). "Dogs with CTLA-4 levels below the cutoff values, which were determined based on receiver operating characteristic curves, on peripheral CD4+, CD8+, and tumor infiltrating CD4+ lymphocytes had significantly longer survival than dogs with values above the cutoff." (PMID 30040869, 2018). "CTLA4 counteracts the activity of the T cell costimulatory receptor CD28 for binding to the B7 ligand expressed on tumor cells and, therefore, CTLA4 functions as a negative immune regulator." (PMID 29942724, 2018). "Consistent with its superior antitumor efficacy, a-CTLA4-TGFβRII was more effective in reducing Tregs, elevating tumor-reactive IFN-γ-expressing CD8+ cells and increasing the CD4+ and CD8+ central memory T cells compared with the combination of a-CTLA-4 and a-PD-1 mAbs." (PMID 29467463, 2018). "In one of these studies, the combination of imatinib that can reduce tumor cell expression of IDO and thus, block IDO-mediated immunosuppression of T cell responses, with anti-CTLA-4 mAb resulted in enhanced antitumor response in a mouse model of gastrointestinal tumors." (PMID 29482595, 2018). "Despite the generally accepted concept that anti-mouse CTLA-4 mAbs induce tumor rejection by blocking negative signaling from the B7-CTLA-4 interaction, the blocking activity of these antibodies have not been critically evaluated." (PMID 29472691, 2018). "Moreover, immunological assessment of the microenvironment in MMRD tumours exhibits enhanced attraction of tumour-infiltrating lymphocytes and widespread expression of several immune checkpoint ligands like PD-L1, LAG-3, IDO, and CTLA4." (PMID 30173350, 2018). "The density of CTLA-4 was significantly higher on the CD39+ Treg compared to the CD39− Treg in all three tissues, and the difference in density between the subsets was largest in tumor-infiltrating Treg." (PMID 30651930, 2018). "Moreover, bindings of H3K9me3 and H3K27me3 were found to be reduced in the promoter loci of PD-1, CTLA-4, TIM-3, and LAG-3 in tumor tissues." (PMID 29983831, 2018). "The number of regulatory T cells (Treg) in the tumor-bearing brain were not significantly affected by dexamethasone or CTLA-4 blockade whereas overall numbers were reduced in TDLNs from each dexamethasone-treated cohort." (PMID 29891009, 2018). "Interestingly, we found that CpG islands in the promoter regions of PD-1, CTLA-4, and TIM-3 were significantly hypomethylated in tumor compared with normal tissues." (PMID 29983831, 2018). "PD-L1 is a nonredundant checkpoint in tumor vaccine therapy, and blocking this checkpoint in combination with whole cell vaccination and CTLA-4 inhibition enables enhanced antitumor T-cell killing." (PMID 29377881, 2018).